IL6 (interleukin 6)
Diseases named in the same sentence as IL6 in open-access papers (continued):
Sharing a sentence is not in itself a finding about the gene and the disease.
myocardial infarction (continued). "In addition, in the PLATO study, higher incidence for the composite outcome of cardiovascular death and myocardial infarction was observed among subjects in the highest quartile of baseline IL-6." (PMID 33495783, 2021). "We further report that the odds of having heart attack in presence of elevated triglycerides and pro-inflammatory parameters (TNFα and IL6) were approximately eight times higher as compared to heart attack in individuals with only elevated levels of pro-inflammatory markers." (PMID 33510184, 2021). "Thus, the role of IL-6 in myocardial infarction in mice is complex, and cytokines remain a difficult target for treatment." (PMID 33428604, 2021). "Taken together, our results show that the odds of having a history of heart attack in presence of elevated triglycerides and pro-inflammatory parameters (TNFα and IL6) are approximately eight fold higher as compared to heart attack with elevation only in the levels of TNFα and IL6." (PMID 33510184, 2021). "This was due to enhanced integrin αIIbβ3 activation of PLD2-deficient platelets under inflammatory conditions, resulting in enhanced IL-6 release of ECs to accelerate inflammation after myocardial infarction, suggesting that PLD2 is an effector of thrombo-inflammation." (PMID 33114406, 2020). "Although increased levels of IL-6 have been reported after myocardial infarction the major source remains unclear." (PMID 32537679, 2020). "So, here, we hypothesize that the presence of IL6 in EV-CDCs, as well as the increase in IFNγ/EV-CDCs, may have a therapeutic effect in the control of acute inflammatory responses in myocardial infarction." (PMID 32582685, 2020). "Elevated IL-6 levels have been reported after myocardial infarction." (PMID 32537679, 2020). "Indeed, Il-6 was elevated in samples of patients with myocardial infarction compared to control samples." (PMID 30948775, 2019). "Serum levels of IL-6 increase after acute myocardial infarction, and since high IL-6 and C-reactive protein levels coincide with peak cardiac troponin, they could confirm the connection between inflammation and infarct size." (PMID 31205590, 2019). "For example, elevated CRP, TNF-α, and IL-6 levels have been associated with both myocardial infarction (MI) and non-traumatic FF." (PMID 30630495, 2019). "Consequently, IL-6 inhibition in myocardial infarction patients led to a lesser degree of left ventricular fibrosis." (PMID 31186952, 2019). "In a meta‐analysis of 29 population‐based prospective studies, IL‐6 was associated with an increase in the adjusted relative risk for nonfatal myocardial infarction or coronary heart disease death." (PMID 29744301, 2018). "This suggests that IL-6 contributes to the pathology of myocardial infarction." (PMID 30423923, 2018). "The increase in IL-10 in myocardial infarct patients was found to be correlated with systemic pro-inflammatory activity evaluated with thrombosis, plaque rupture and heart destruction related to IL-6 and TNF-α plasma concentrations." (PMID 29742255, 2018). "Inflammatory biomarkers (tumor necrosis factor alpha and interleukin-6) were reduced and pro-angiogenesis factors (vascular endothelial growth factor and platelet/endothelial cell adhesion molecule 1) were augmented in the myocardial infarct and border area." (PMID 29751831, 2018). "Moreover, IL-6 and its receptor levels have an early peak in the acute phase of myocardial infarction, probably due to plaque instability." (PMID 30223482, 2018). "IL-6 rapidly increases in response to ischemia in acute myocardial infarction." (PMID 30423923, 2018). "They reported that as blood pressure increased, IL-6 levels and associated cardiovascular mortality increased, concluding that IL-6 plasma levels could be used as predictors of future myocardial infarction." (PMID 27213076, 2016). "Interleukin-6 (IL-6) levels are upregulated in myocardial infarction." (PMID 27936014, 2016).
myocardial infarction (continued). "Different inflammatory markers such as C-reactive protein (CRP) or pro-inflammatory cytokines such as interleukin-6 or interleukin-1 have been shown to be elevated in patients with myocardial infarction or unstable angina, reflecting low-grade inflammatory status in the vascular bed." (PMID 26340022, 2015). "We thought we could add to this debate by examining if serum levels of IL-6 recorded at admission predict 30-day mortality in patients with myocardial infarction." (PMID 25516764, 2014). "Also, it was reported that QSYQ can inhibit inflammatory effect through reducing TNF-α and IL-6 levels in rat after acute myocardial infarction." (PMID 24817581, 2014). "IL-6 though might exert dynamic actions and act as a potent “myokine”, where in a rapid response to acute myocardial infarction it activates cardioprotective pathways, resulting in increase in cardiomyocyte proliferation." (PMID 23406316, 2013). "The in vitro hypoxic and pro-inflammatory preconditioning of ADSC i. e. mimicking the post-myocardial infarction microenvironment (ischemia and inflammation), strongly upregulated the IL-6 production by ADSC and further augmented the stimulation of the proliferation of cardiomyocytes." (PMID 23406316, 2013). "Cardiac overexpression of TNF-α has been associated with cardiac hypertrophy and fibrosis, as well with left ventricular dysfunction and IL-6 has been also described as an inducer of myocardial damage by promoting LV dysfunction and cardiac hypertrophy under acute myocardial infarction." (PMID 23497124, 2013). "This elevation may be clinically significant, since equivalent increases in circulating IL-6 (in healthy adults) have been shown to predict myocardial infarction." (PMID 22685596, 2012). "In addition, fibrin beta decreases myocardial infarct size, scar formation, inflammation and the levels of cytokines (interleukin 1 beta, tumor necrosis factor-alpha and interleukin 6) in plasma." (PMID 23139772, 2012). "Epidemiological findings in the region of Augsburg, Germany, showed that elevated levels of PM are associated with an increased incidence of myocardial infarction and also with increased levels of markers indicative for early systemic effects, like CRP and IL-6, or with plasma viscosity." (PMID 20920269, 2010). "In conclusion, our results support the hypothesis that a genetic interaction between the thrombin receptor and the interleukin 6 gene plays a role in the occurrence of myocardial infarction." (PMID 20585578, 2010). "In atherosclerotic heart disease, including myocardial infarction (MI), IL-6 is also produced by and have effects on cardiomyocytes." (PMID 41543641, 2026). "In patients with myocardial infarction (MI), elevated serum Il6 levels measured on the first day after angioplasty are closely correlated with the subsequent development of heart failure." (PMID 41347019, 2025). "M1 macrophages produce inflammatory cytokines such as TNF-α and IL-6, which drive the progression of atherosclerotic plaques and contribute to myocardial damage post-myocardial infarction (MI)." (PMID 39736852, 2025). "Moreover, the selective inhibition of the IL-6 trans-signaling pathway, which mediates pro-inflammatory IL-6 effects in a rat model of re-perfused myocardial infarction, prevented IL-6 pro-inflammatory defects, reduced infarct size, and preserved cardiac function." (PMID 39125976, 2024). "Moreover, nalbuphine could efficiently improve the hemodynamic perturbation in myocardial infarction and exert an anti-inflammatory potential via inhibiting NF-κB-induced IL-6 and TNF-α production." (PMID 39272237, 2024).
myocardial infarction (continued). "In addition, IL-6 and CRP may be associated with diagnosis, risk stratification and prognosis in patients with acute myocardial infarction, and both are also significantly upregulated in acute coronary syndromes." (PMID 37485268, 2023). "The analysis of the ROC curve performed in myocardial infarction patients showed that IL-6 (AUC: 0.941 (CI 95% 0.886, 0.997; p < 0.001) could be a powerful predictor marker in evaluating the infarct size after myocardial infarction when compared to myonecrosis biomarkers." (PMID 38017432, 2023). "Studies in mouse models of Alzheimer’s disease, brain injury, myocardial infarction and inflammatory bowel disease could demonstrate a reduction in expression levels of interleukin-1 beta, interleukin-6, MCP-1 and NLRP3 upon treatment with pterostilbene and prebiotics." (PMID 36906614, 2023). "After myocardial infarction (MI), serum levels of IL-6 increase rapidly, correlating with the severity of tissue injury, and remain elevated for several weeks." (PMID 36943408, 2023). "Furthermore, our data indicated that Turicibacter was obviously and negatively correlated with serum cTnI and CK levels, the myocardial infarct area, HE score, apoptosis rate, inflammatory factors (IL-1β, IL-6, and TNF-α) in colon and ileum and serum LPS and Zonulin concentration." (PMID 37656700, 2023). "In a large meta-analysis examining data from multiple prospective studies, elevated levels of CRP, interleukin-6 (IL-6), and fibrinogen were associated with an increased risk of major cardiovascular events, including heart attacks and strokes in both diabetic and non-diabetic populations." (PMID 38104079, 2023). "The group receiving this treatment had improved cardiac contractility at 5 weeks post myocardial infarction and enhanced blood vessel density in the border zone of the infarct, decreased interstitial fibrosis, and reduced levels of the plasma pro-inflammatory cytokines (IL-6 and TNF-α)." (PMID 36263604, 2023). "In the ASSessing the effect of Anti-IL-6 treatment in Myocardial Infarction (ASSAIL-MI) trial, we showed that tocilizumab increased the myocardial salvage index (MSI) evaluated by cardiac MR imaging (CMR) in patients with ST-segment elevation MI (STEMI)." (PMID 37591633, 2023). "In addition, polymorphisms, haplotypes and variability in plasma levels of C-reactive protein, fibrinogen, IL-6 may have altered the pro-inflammatory response of air pollution in myocardial infarction patients." (PMID 35354890, 2022). "In addition, a cardio-protective effect has also been reported for PTX3 in murine models of acute myocardial infarction, and increased plasma levels and cardiac expressions of IL-6 and generation of ROS have been shown in the ischemic myocardium of PTX3-knock out animals." (PMID 36362273, 2022). "Interestingly, IL-6 seems to be a driver for proinflammatory responses related to the impairment of microcirculation, affecting the recovery of ischemic tissue post myocardial infarction." (PMID 33495783, 2021). "Moreover, as in the case of elevated IL-6 expression, high levels of IL-1Ra in patients with HIV monoinfection are associated with an increased risk of cardiovascular diseases; in particular, a 1.5-fold increased risk of myocardial infarction." (PMID 34835417, 2021). "Increased levels of CRP and interleukin-6 at hospital admission, in conjunction with increased BNP (brain natriuretic peptide) biomarker in convalescence, reflect the association between ventricular remodelling after myocardial infarction and impaired renal function." (PMID 32182690, 2020). "For instance, according to a recent meta-analysis of prospective population-based studies, a one standard deviation increased baseline level for loge IL-6 predicted a 25% adjusted higher relative risk of non-fatal myocardial infarction or coronary heart disease (CHD) mortality." (PMID 31798472, 2019).
myocardial infarction (continued). "The level of systemic inflammation will be evaluated based on the serum biomarker levels (hs-CRP, matrix metalloproteinases, interleukin-6) in the acute phase of the myocardial infarction (MI) and at 1 month." (PMID 31027064, 2019). "As we do not have the blood levels of Il-6 prior to the event, it is impossible to discern whether this serum property is a cause or a consequence of VF during myocardial infarction." (PMID 30948775, 2019). "These PICs include tumor necrosis factor-alpha (TNF-α), interleukin-1β (IL-1β) and IL-6, which are released into the circulation early after myocardial infarction (MI)." (PMID 25984330, 2014). "Positive correlations have been established between acute myocardial infarction and elevated levels of pro-inflammatory cytokines such as TNF-α, IL-6, and IL-1β." (PMID 41599430, 2026). "IL-6 is elevated in patients with ACS, especially in those with unstable angina and acute myocardial infarction, reflecting increased inflammatory activity within atherosclerotic plaques." (PMID 41511355, 2025). "In acute myocardial infarction, low FT3, normal or low TSH, and high IL-6 and its soluble receptor were observed." (PMID 40870417, 2025). "IL-6 levels are strongly associated with mortality in patients with unstable CAD, independent of traditional risk factors such as age, sex, diabetes, and previous myocardial infarction (MI)." (PMID 40244022, 2025). "Importantly, TXA did not elevate the risk of postoperative complications (e.g., mortality, myocardial infarction, cerebrovascular accidents, thrombotic events) and had no impact on levels of CK-MB, creatinine, interleukin-6, or lengths of intensive care unit (ICU) and hospital stays." (PMID 40978753, 2025). "A randomized, placebo-controlled trial, ASSessing the effect of Anti-IL-6 treatment in Myocardial Infarction (ASSAIL-MI), demonstrated that IL-6R inhibition with tocilizumab administered during PCI in patients with STEMI reduced the inflammatory response and myocardial damage." (PMID 40508157, 2025). "In previous studies, the anti-inflammatory effects of chokeberry, expressed as a reduction in inflammatory markers such as C-reactive protein (CRP), IL-6, and VCAM-1, were observed in post-myocardial infarction patients taking chokeberry extract." (PMID 39859963, 2024). "In all cases of myocardial infarction, median serum levels of hs-CRP, IL-6, NF-κB, TNF-α and VCAM-1 were 1.31 mg/L, 11.88 pg/ml, 11.34 ng/ml, 2.19 pg/ml and 1157.37 ng/ml, respectively." (PMID 39351476, 2024). "In contrast, exosomes from adipose-derived MSCs exhibit reduced levels of inflammatory markers as IL-1β, IL-6, TNF-α, and IFN-γ in patients with myocardial infarction." (PMID 39911664, 2024). "Treatment with curcumin showed a reduction in the levels of inflammatory mediators, such as IL-6, IL-1β, and TNF-α, in the myocardium in diabetic mice with myocardial infarction." (PMID 38338960, 2024). "Other examples are PD-1 and IL6 signaling (Cardiomyopathy) and TGF-beta signaling (Myocardial Infarction)." (PMID 37491351, 2023). "For example, in heart failure (HF) induced by myocardial infarction (MI), it is possible to observe an increase in interleukin 1 beta (IL-1β), tumor necrosis factor alpha (TNF-α), interleukin 6 (IL-6), and lectin 3 levels." (PMID 36831272, 2023). "Inflammatory cytokines, such as IL-1, IL-6, and TNF-α, have been shown to increase dramatically after myocardial infarction and are involved in future LV remodeling." (PMID 35538296, 2023). "Although the significant increase in IL-6 was lost at follow-up, TNF-α levels remained significantly increased 1 year after myocardial infarction." (PMID 35681518, 2022). "Furthermore, during myocardial infarct, it has been described a significant stimulation of D3 activity, probably caused by the chronic inflammation promoted by the Tumor Necrosis Factor- α (TNF-α) and the Interleukin-6 (IL-6) release, thus complicating the hypothyroid condition." (PMID 36676947, 2022).
myocardial infarction (continued). "Recently, in assessing the effect of Anti-IL-6 treatment in a myocardial infarction (ASSAIL-MI) trial, IL-6 inhibition by tocilizumab was reported to increase myocardial salvage in patients with acute STEMI." (PMID 35406729, 2022). "Administration of FGF21 decreased the mRNA expression of interleukin-6 (IL-6) and tumor necrosis factor-α (TNF-α) and protected against pathological myocardial remodeling and improved cardiac function at 2 weeks in a myocardial infarction mouse model." (PMID 36440004, 2022). "After myocardial infarction diabetic patients also show higher inflammatory activity measured by elevated markers of inflammation (CRP and IL-6)." (PMID 35845058, 2022). "The increase in IL-6 levels has a strong relationship with future cardiac events and CAD mortality in anginal syndrome or healed myocardial infarction patients." (PMID 35402550, 2022). "The objectives of the present study were to further explore IL-6 signalling during acute myocardial infarction (MI) by studying the potential role of acute and sustained IL-6 and soluble IL-6R elevation up to 4 months post-MI." (PMID 34933964, 2021). "Shenmai-Danshen (SM-DS) injection im-proved MDA, SOD, interleukin 6 (IL-6), and TNF-alpha levels and reduced the myocardial reperfusion injury in patients with acute myocardial infarction, after percutaneous coronary intervention (PCI)." (PMID 34790246, 2021). "NF-κB is a multiple transcription factor that regulates transcription of various genes involved in the pathogenesis of myocardial infarction like TNF-α and IL-6." (PMID 34266475, 2021). "Plasma concentrations of IL-6 and hs-CRP (inflammation markers) have predictive value for the prognosis of patients with myocardial infarction." (PMID 34231707, 2021). "Several studies have described an increased expression of proinflammatory cytokines IL-1β, IL-6, and TNF-α in ISO-induced myocardial infarction." (PMID 34072098, 2021). "In the mouse model of hindlimb ischemia and myocardial infarction, human MSC activates M2 macrophages through IL-6 secretion." (PMID 33741073, 2021). "The association between interleukin-6 (IL-6) gene −572 G^C polymorphism and myocardial infarction (MI) risk has not been established." (PMID 33335998, 2020). "Typhaneoside regulates IL-6 and TNF-α as well as MMP-2 and MMP-9 in rats with heart failure after myocardial infarction." (PMID 31201434, 2020). "In our results, after knockdown RXFP1 by specific RXFP1 siRNA, mast cell markers chymase and tryptase, inflammatory cytokines IL-6 and TNF-α, and classic phosphorylated NF-κB all increased, which was consistent with the acute myocardial infarction outcomes." (PMID 32859236, 2020). "Post-myocardial infarction patients have increased circulating mDNA levels, accompanied by higher levels of inflammatory cytokines, such as TNF-α and IL-6, compared to healthy individuals." (PMID 32009974, 2019). "In the present study, myocardial infarction increased the TNF-α and IL-6 levels in normotensive and L-NAME-induced hypertensive rats." (PMID 31052164, 2019). "We compared myocardial infarct size, serum levels of cTnI, and expression of HMGB1, TNF-α, and IL-6 in the myocardium and serum in all groups after 120 min of reperfusion." (PMID 31344138, 2019). "AMI: acute myocardial infarction; CRP: C-reactive protein; IL-6: interleukin-6; VCAM-1: vascular cell adhesion molecule 1; ICAM-1: intercellular adhesion molecule-1; ACEi: angiotensin-converting enzyme inhibitors; ARBs: angiotensin II receptor blockers." (PMID 31778438, 2019). "For instance, in response to acute myocardial infarction, there is an early increase of proinflammatory cytokines, such as TNF-alpha, IL-6, IL-1beta, and transforming growth factor 1-beta (TGF-1beta)." (PMID 30935055, 2019). "Previous study on serum leptin, IL-6 and hs-CRP levels have been conducted in acute myocardial infarction (AMI) patients from south India (Chennai)." (PMID 30001365, 2018).